HDAC3 (histone deacetylase 3)
Diseases named in the same sentence as HDAC3 in open-access papers (continued):
Sharing a sentence is not in itself a finding about the gene and the disease.
Obesity (continued). "While we cannot with certainty define the mode of action for HDAC3 in the regulation of systemic adiposity, our findings clearly establish that inhibiting intestinal HDAC3 has the capacity for therapeutic utility in the treatment of obesity and metabolic co-morbidities." (PMID 31757939, 2019). "Notably, alterations in the expression and function of the histone deacetylase 3 (HDAC3) corepressor complex in macrophages and adipocytes have been linked to metabolic-inflammatory diseases, such as obesity and type 2 diabetes in humans." (PMID 30975991, 2019). "We also demonstrate that intestinal-specific deletion of Hdac3 protects against adiposity, suggesting HDAC3 may represent a potential therapeutic target in preventing obesity and related diseases." (PMID 31757939, 2019). "Having observed profound remodeling of WAT metabolism in H3atKO mice, we investigated whether adipose ablation of HDAC3 was able to prevent or attenuate diet-induced obesity." (PMID 28733645, 2017). "Therefore, we could assume that CR disorders may alter the GM with subsequent disruption of the HDAC3 pathway, thereby contributing to explaining obesity and T2DM in patients with circadian sleep alterations." (PMID 37445790, 2023). "Thus, SCFA (mainly butyrate) prevent diet-induced obesity by inhibiting HDAC3 activity in IECs, and attempts to regulate the butyrate-HDAC3 pathway may be used to prevent and ameliorate obesity-related diseases." (PMID 35662937, 2022). "Therefore, selective HDAC3 inhibitors might represent a potential therapeutic strategy in the treatment of obesity." (PMID 34829943, 2021). "The epithelial histone deacetylase 3 (HDAC3) can alter lipid uptake of the intestine as a result of fluctuations induced by histone acetylation mediated by microbiota and induce obesity in affected humans." (PMID 39210613, 2024). "Finally, we determined whether deletion of Hdac3 in IECs protects against HFD-induced obesity." (PMID 31757939, 2019). "HDAC3 also synergistically activates estrogen-related receptor α (ERRα), induces microbiota-dependent rhythmic transcription of the lipid transporter gene CD36, and promotes lipid absorption and diet-induced obesity." (PMID 34203243, 2021). "We propose that by regulating HDAC3 activity during cellular damage, DBC1 participates in the fate decision that leads to the establishment of cellular senescence and consequently to inflammation and tissue dysfunction during obesity." (PMID 24992635, 2014). "Taken together, these results suggest that HDAC3 inhibition rather than HDAC1/2 inhibition by MS-275 protects against lipotoxicity in C2C12 myotubes and skeletal muscle, and may be effective for the treatment of obesity and insulin resistance." (PMID 33362555, 2020).
prostate carcinoma (31 papers, 2008 to 2025). A carcinoma that arises from epithelial cells of the prostate gland. "Depletion of HDAC3 or other HDACs suppresses expression of AR and its downstream target genes in prostate cancer cells, although the underlying mechanism remains poorly understood." (PMID 29523594, 2018). "Together, these data indicate that the HDAC3 inhibitor blocks PTEN‐mutated prostate cancer cell growth by targeting both AKT and AR signaling." (PMID 29523594, 2018). "Thus, our data suggest that inhibition of HDAC3 effectively suppresses the growth of SPOP‐mutated prostate cancer cells by shutting down both AKT and AR signaling pathways." (PMID 29523594, 2018). "We found that the gene expression of KCa3.1 and ANO1 was epigenetically regulated by HDAC3 in breast and prostate cancers." (PMID 39273558, 2024). "In the present study, we specifically targeted HDAC3 in prostate cancer cells, highlighting a potential role for the ERG-NCoR-HDAC3 pathway in nonhematologic malignancies characterized by altered ERG expression." (PMID 37735473, 2023). "The results also showed that VA possessed the anti-proliferative ability in prostate cancer cells and such ability was partly exerted by inhibiting HDAC3." (PMID 36175803, 2022). "Meanwhile, it has been found that overexpression of HDAC3 has been found in a positive correlation with the proliferation, development, and poor prognosis of prostate cancer." (PMID 36175803, 2022). "RT-qPCR results displayed that both prostate cancer cell lines had higher HDAC3 expression compared to two normal prostate cell lines, respectively." (PMID 36175803, 2022). "Examination of molecular pathways demonstrates that KLF5 inhibits BECN1 and HDAC3 (histone deacetylase 3) cooperation to suppress autophagy and promote docetaxel sensitivity in the context of prostate cancer." (PMID 35317831, 2022). "HDACs are overexpressed in many human cancers, including prostate cancer, and the overexpression of HDAC3 has been found in a positive correlation with the proliferation, development, and poor prognosis of prostate cancer." (PMID 36175803, 2022). "More specifically, it inhibits the expression of HDAC3 therefore suppressing the proliferation of prostate cancer cells." (PMID 36175803, 2022). "In line with these theoretic results, our in vitro cell line results have further validated the inhibitive effect of VA on expression of HDAC3 in prostate cancer cells and HDAC3 activity levels." (PMID 36175803, 2022). "Recently, HDAC3 was shown to interact with KLF5 to promote prostate cancer autophagy in response to docetaxel treatment." (PMID 35342356, 2022). "The findings suggest that VA acts as a HDAC3 inhibitor with anti-cancer effect on prostate cancer by regulating E2F1/E2F3/CASP3 axis." (PMID 36175803, 2022). "In prostate cancer, for example, HDAC3 interacts with the SP1 site on the miR-451 promoter, increasing the miR-451 promoter histone deacetylation to inhibit miR-451 expression." (PMID 33718133, 2021). "Broccoli sprouts and sulforaphane have been shown to reduce prostate cancer incidence through reduction of histone deacetylation 3 (HDAC3) in mice, and altering global DNA methylation in prostate cell models." (PMID 30982861, 2019). "In human prostate cancer organoids and xenograft models, we further showed that a selective HDAC3 inhibitor is efficacious in inhibition of AKT and AR signaling in both PTEN‐ and SPOP‐mutant background." (PMID 29523594, 2018). "Treatment of prostate cancer cells with HDAC3‐specific inhibitor not only inhibits AKT‐mTORC1 signaling, but also suppresses expression of AR and its downstream target genes." (PMID 29523594, 2018). "HDAC3 inhibitor shows efficacy in these two prostate cancer subtypes that share activated AR and AKT pathways." (PMID 29572264, 2018).
prostate carcinoma (continued). "Pharmacological inhibition of HDAC3 using a selective HDAC3 inhibitor RGFP966 inhibits growth of both PTEN‐deficient and SPOP‐mutated prostate cancer cells in culture, patient‐derived organoids and xenografts in mice." (PMID 29523594, 2018). "HDAC3 is overexpressed in a majority of prostate cancers, implying a role of HDAC3 in prostate tumorigenesis." (PMID 29523594, 2018). "Here, we demonstrate that HDAC3 augments AKT phosphorylation in prostate cancer cells and its overexpression correlates with AKT phosphorylation in patient samples." (PMID 29523594, 2018). "Through unbiased shRNA screening, we demonstrated for the first time that HDAC3 is the only member of the class I/II HDAC subfamily that regulates AKT phosphorylation in C4‐2 prostate cancer cells." (PMID 29523594, 2018). "On the contrary, we observed that 22Rv1 (IC50: 0.720 μM) was more sensitive to RGFP966 compared with C4‐2 (IC50: 1.19 μM), indicating that PTEN status is a potential determinant of the efficacy of HDAC3 inhibitor in prostate cancer treatment." (PMID 29523594, 2018). "In the present study, we demonstrated that HDAC3 is required for AKT phosphorylation in prostate cancer cells." (PMID 29523594, 2018). "Our data suggest that dual inhibition of AKT and AR signaling in prostate cancer, especially in those with genetic alterations such as PTEN loss, can be achieved by single administration of HDAC3‐specific inhibitor." (PMID 29523594, 2018). "As expected, AKT phosphorylation was elevated by PTEN knockdown in PTEN‐positive 22Rv1 prostate cancer cells, but PTEN loss‐enhanced AKT phosphorylation was mitigated by HDAC3 co‐knockdown." (PMID 29523594, 2018). "In concordance with our findings in prostate cancer cells, a recent chemoresistance study showed that HDAC3 regulates AKT phosphorylation in acute myeloid leukemia." (PMID 29523594, 2018). "Our study identifies HDAC3 as a common upstream activator of AKT and AR signaling and reveals that dual inhibition of AKT and AR pathways is achievable by single‐agent targeting of HDAC3 in prostate cancer." (PMID 29523594, 2018). "Taken together, our findings reveal that HDAC3 is a critical factor in delphinidin-induced apoptosis in human prostate cancer LNCaP cells." (PMID 27462923, 2016). "A further study shows that HDAC3 is strongly expressed in over 90% of prostate cancer samples tested." (PMID 26450925, 2015). "In conclusion, delphinidin sensitizes prostate cancer cells to TRAIL-induced apoptosis by inducing DR5, thus causing caspase-mediated HDAC3 cleavage." (PMID 25991668, 2015). "We found that blocking HDAC3 activity using MI192, a compound specific for HDAC3, modulated tubulin acetylation in the human prostate cancer cell line PC3." (PMID 26450925, 2015). "A previous article reported the binding between SFMBT2 and HDAC3 in prostate cancer cells." (PMID 38734627, 2024). "We therefore investigated the effect of HDAC3 inhibition on the survival of prostate cancer cells." (PMID 37735473, 2023). "Additionally, the suppression of HDAC3 is proved to discourage xenografted tumor growth in prostate cancer." (PMID 33203425, 2020). "Blocking HDAC3 activity could dramatically alter the tubulin acetylation in the human prostate cancer cells." (PMID 31498540, 2019). "Interestingly, the steep curves of the clonogenic survival data clearly showed that both cell lines were more sensitive to RGFP966 than GDC0068, suggesting that prostate cancer cells are vulnerable to HDAC3 inhibition." (PMID 29523594, 2018).
prostate carcinoma (continued). "Also, we find that delphinidin-mediated TRAIL sensitization in prostate cancer cells seem to be associated with activation of effector caspases via induction of the DR5 pathway, leading to HDAC3 cleavage-dependent mitochondrial apoptosis." (PMID 25991668, 2015). "In addition, expression of HDAC1 (P=0.032), HDAC2 (P=0.002) and HDAC3 (P<0.001) correlated significantly with the Ki-67-positive proliferative fraction of prostate cancer cells." (PMID 18212746, 2008). "The high percentage of HDAC3 positivity (95%) in prostate cancer naturally compromised valid correlations and survival analyses but may make this isoform interesting in terms of a therapy target." (PMID 18212746, 2008). "The consistently high rate of HDAC3 positivity in prostate cancer might be of interest for further exploratory therapeutic studies." (PMID 18212746, 2008). "Interestingly, KLF5 could inhibit prostate cancer cell autophagy by suppressing the transcription of BECN1 cooperatively with HDAC3." (PMID 31534497, 2019). "Interestingly, we found that KLF5 could inhibit prostate cancer cell autophagy via suppressing the transcription of BECN1 cooperatively with HDAC3." (PMID 31534497, 2019). "Therefore, HDAC3 might be an essential upstream regulator of AKT phosphorylation in prostate cancer cells in culture and in patients." (PMID 29523594, 2018). "Therefore, based on the findings in this study and others, there are several reasons that inhibition of HDAC3 might be an ideal target for the treatment of prostate cancer." (PMID 29523594, 2018). "Again, studies in other tumor entities revealed an ambiguous picture, with the HDAC1-, HDAC3- and HDAC6-specific inhibitor SN30028 leading to a persistent downregulation of amphiregulin in the prostate carcinoma cell line PC3." (PMID 39864337, 2025). "Chidamide, in contrast, selectively targets HDAC1, HDAC2, HDAC3, and HDAC10, aligning closely with the four HDAC isoforms most overexpressed in prostate cancer, making it a more biologically relevant candidate for mCRPC treatment." (PMID 41200281, 2025). "Inhibiting HDAC3 reduces the growth of ERG-dependent leukemic and prostate cancer cells, indicating that the interaction between ERG and the NCoR-HDAC3 co-repressor complex is crucial for its oncogenic activity." (PMID 37735473, 2023). "In prostate cancer cells, KLF5 collaborates with HDAC3 to inhibit Beclin1 transcription and reduce autophagy." (PMID 37391422, 2023). "Functional, genetic, and biochemical studies revealed that P199 contributes to the ERG-NCoR-HDAC3 interaction, thereby highlighting HDAC3 as a potential therapeutic target for ERG-mediated leukemias and, possibly, other malignancies such as prostate cancer." (PMID 37735473, 2023). "We analyzed the expression of DNMT1, DNMT3A, DNMT3B, and the class I HDACs HDAC1, HDAC2, HDAC3, and HDAC8 in the PRAD and Taylor data sets and their correlation to HLA-I expression in prostate cancer." (PMID 36050516, 2022). "For example, compound 11b, an indomethacin-SAHA fusion molecule that selectively inhibits COX2 and HDAC6 > HDAC8 > HDAC3 > HDAC2 > HDAC1, inhibits the proliferation of androgen-dependent prostate carcinoma cells." (PMID 31561534, 2019). "In summary, our findings have demonstrated for the first time that the cytoplasmic (non‐genomic) activity of HDAC3 is required for AKT phosphorylation and AR upregulation in prostate cancer cells." (PMID 29523594, 2018). "We further examined the correlation between HDAC3 protein expression and AKT phosphorylation by performing immunohistochemistry (IHC) on a tissue microarray (TMA) containing 55 prostate cancer samples." (PMID 29523594, 2018). "In this study, we reveal a positive correlation between HDAC3 expression and AKT phosphorylation at the molecular level, a spontaneous prostate cancer mouse model, tumor‐derived organoids, and patient specimens." (PMID 29523594, 2018).
prostate carcinoma (continued). "TRAIL-induced apoptosis in prostate cancer cells pretreated with delphinidin was dependent on death receptor 5 (DR5) and downstream cleavage of histone deacetylase 3 (HDAC3)." (PMID 25991668, 2015). "Previous study reported that in prostate cancer cells, KLF5 could collaborate with HDAC3 to repress BECN1 transcription." (PMID 40659605, 2025). "Furthermore, Western blot analysis demonstrated that saffron treatment induced changes in the expression of other key genes (DNMT1, DNMT3b, MBD2, CD44, HDAC3, c-Myc, NF-kB, TNFα, AR, N-RAS, and PTEN) in prostate cancer cells." (PMID 38201944, 2023). "HDAC3, which is upregulated in prostate cancer, facilitates lysine‐63‐chain polyubiquitination and phosphorylation of AKT in prostate cancer cells, a non‐nuclear effect mediated by AKT deacetylation at lysine 14 and 20 residues and HDAC3 interaction with the scaffold protein APPL1." (PMID 29572264, 2018). "Specifically, comparison of 52 paired normal and tumor samples showed that the majority of them [approximately 56% (29 out of 52)] exhibited an increased expression of HDAC3 at the mRNA level in tumors (Fig EV1B), suggesting that HDAC3 is a highly relevant protein in prostate cancer." (PMID 29523594, 2018). "Furthermore, in prostate cancer, apigenin treatment induced cell cycle arrest and apoptosis, thus significantly inhibiting tumour growth in mice by inhibiting Histone deacetylases (HDACs), especially HDAC1 and HDAC3 expression in prostate cancer cells." (PMID 36557789, 2022). "Given that selective HDAC3 inhibitor RGFP966 exhibited a pronounced anti‐cancer effect in hematological malignancies, we sought to determine whether RGFP966 inhibits cell growth of solid tumors such as prostate cancer." (PMID 29523594, 2018).